PPARG (peroxisome proliferator activated receptor gamma)
Diseases named in the same sentence as PPARG in open-access papers (continued):
Sharing a sentence is not in itself a finding about the gene and the disease.
type 2 diabetes (continued). "Apart from insulin, glimepiride, a third generation sulfonylurea, pioglitazone, a peroxisome proliferator-activated receptor gamma (PPAR-γ) agonist, and a member of the thiazolidinedione family (TZD), and metformin, a biguanide, are used for treatment of type 2 diabetes." (PMID 22436702, 2012). "Thus, compounds that stimulate both PPARα and PPARγ (dual PPARα/γ agonists) should additively improve both lipid and glucose abnormalities in animal models and human subjects with insulin resistance (IR) and/or type 2 diabetes (T2DM)." (PMID 23226761, 2012). "Ligands for PPARγ include polyunsaturated fatty acids and synthetically derived thiazolidinedione (TZD) ligands for PPARγ that improve insulin sensitivity in patients with type 2 diabetes." (PMID 21533082, 2011). "Pioglitazone, a PPARγ activator, shifts the circadian rhythm of blood pressure from nondipper to dipper type 2 diabetes patients." (PMID 20706650, 2010). "In type 2 diabetic patients, the anti-inflammatory effect of rosiglitazone is not reflected by changes in NFκB and PPARγ target genes in PBMCs in vivo." (PMID 19243600, 2009). "Fat infiltration-related genes (FABP and PPARγ) expression tended to increase in supraspinatus muscle specimens, and fat infiltration developed gradually over time, with FABP4 mRNA expression levels significantly increasing in the 2-week group after type 2 diabetes induction (p < 0.05)." (PMID 36299460, 2022). "Thus, PPARγ and IRS1 are related to insulin resistance and type 2 diabetes mellitus." (PMID 36292779, 2022). "They tested the type II diabetes–related genes in LPS-induced RAW 264.7 cells and found that LPS could greatly increase the levels of RANTES, 11β-HSD1, and PPARγ genes; however, type II diabetes–related genes decreased signifcantly in the cordycepin-treated group." (PMID 33328984, 2020). "However, we note that other PPARγ agonists have been reported to reduce RARRES2 mRNA levels in epididymal and mesenteric adipose tissue when administered to mice, and plasma chemerin levels when administered to patients with type 2 diabetes." (PMID 25699203, 2015). "PPARγ agonists are used by millions of people each year to treat type 2 diabetes but may also find additional utility as relatively nontoxic potentiators of chemotherapy." (PMID 18566686, 2008). "Additionally, we do not discard the possibility that MpHE through the activation of PPARγ, prevents IKK activity and therefore IRS phosphorylation on serine residues, thus improving insulin signaling directly on hippocampal neurons reversing the memory deficits observed in type II diabetes and AD." (PMID 31291963, 2019). "Synthetic PPARγ agonists (thiazolidinediones), such as rosiglitazone (ROSI), pioglitazone, and troglitazone, have been used for many years in patients with type 2 diabetes (T2DM) to improve insulin resistance and ameliorate hyperglycemia." (PMID 25361524, 2014). "Additionally, SUMOylation (SUMO) was identified as a regulator of PPARγ activity in our PPI analysis, offering a potential strategy for developing safer drugs for treating type 2 diabetes by inhibiting insulin-sensitizing activity without affecting adiposity in mice." (PMID 37445596, 2023).
Hepatic steatosis (418 papers, 2007 to 2026). Steatosis is a term used to denote lipid accumulation within hepatocytes. "The loss of hepatocyte-specific expression of PPARγ (PpargΔHep) reduces diet-induced liver steatosis and slows the progression of steatohepatitis in mice fed a methionine/choline-deficient (MCD) diet." (PMID 40235530, 2025). "Mice with adeno-associated virus-mediated IRF8 overexpression exhibited hepatic steatosis due to up-regulated peroxisome proliferator-activated receptor γ (PPARγ) expression and increased fatty acid uptake and lipogenesis." (PMID 40083324, 2025). "PPARγ overexpression induces hepatic steatosis, while its activation is linked to lipid accumulation and inflammatory signaling." (PMID 41244823, 2025). "Excessive PPARγ expression in hepatocytes has been linked to increased lipogenesis and lipid deposition, exacerbating hepatic steatosis and MASH progression." (PMID 40235530, 2025). "The aim of this study was to investigate the improving effect of Schisandrin B (Sch B) on metabolic associated fatty liver disease (MAFLD) by regulating the PPARγ signaling pathway and gut microbiota, and its mechanism in mice." (PMID 40786039, 2025). "In NAFLD, PPARγ activation is linked to promoting lipid storage in adipose tissue rather than in the liver, potentially offering protection against hepatic steatosis." (PMID 39872862, 2024). "Among these genes, several have been previously linked to the development of fatty liver, including Acaca, Fasn, Pparγ, Cidea, cardiotrophin-like cytokine factor 1 (Clcf1), and Acly." (PMID 39873004, 2024). "NAFLD models of mice rendered deficient in hepatocyte-specific PPARγ had reduced hepatic steatosis relative to PPARγ-intact counterparts, whereas adipose tissue-specific PPARγ knockout mice were lipodystrophy but associated with fatty liver." (PMID 37813918, 2023). "SHP promotes early fatty liver by inducing PPARγ, whereas loss of SHP aggravates hepatic inflammation and liver cancer." (PMID 35614477, 2022). "The effect is associated with a downregulation of the expression of PPARγ, which is a marker of hepatic steatosis, and the upregulation of PLIN3, which is known to be involved in the activation of lipophagy." (PMID 36364243, 2022). "In the liver, increased expression of Pparγ, Scd1, Srebp, and Fabp1 is associated with hepatic steatosis." (PMID 33983968, 2021). "As previously reported, in lipid-overloaded FaO cells hepatic steatosis was associated with an increase in PPARγ expression." (PMID 33671715, 2021). "PPARγ-independent effects of Pio have also been implicated as candidate mediators of Pio's beneficial effects on hepatic steatosis in experimental models." (PMID 32963510, 2020). "We provide evidence that, in aged rats, FoxO1 interaction with PPARγ promotes hepatic steatosis, due to hyperglycemia-induced ER stress, which causes an impairment in Akt signaling, such in aging-related diabetes." (PMID 31235676, 2019). "It is known that FoxO1 and PPARγ are closely associated with hepatic steatosis and our study provides additional evidence that ER stress induces hepatic steatosis through FoxO1-induced PPARγ upregulation." (PMID 31246177, 2019). "In contrast, increased PPARγ expression was associated with the development of hepatic steatosis and lipotoxicity in GY zebrafish." (PMID 31018521, 2019). "Nevertheless, the reduction in hepatic steatosis and fibrosis in groups treated with P. niruri extract and metformin is associated with an effective reduction in the hepatic mRNA of PPARγ, SLC10A2, and Coll α1." (PMID 30096951, 2018). "When considered within a wider clinical context, our results suggest that a better fat storage capacity of adipose tissue depending on optimal levels of PPARγ and C/EBPα is essential for reducing the risk of hepatic steatosis." (PMID 29656108, 2018).
Hepatic steatosis (continued). "Liver PPARγ regulates fatty acid uptake, and trafficking, as well as TG biosynthesis, which contributes to hepatic steatosis and demonstrates positive associations with serum insulin levels and HOMA-IR and negative correlations with total adiponectin." (PMID 28578672, 2017). "Together, we demonstrate that enhanced PPARγ transcriptional activity by RORα deficiency is de-activated by PPARγ antagonism to restore metabolic homeostasis, including body weight gain, hepatic steatosis and glucose and lipid metabolism." (PMID 28757615, 2017). "The lipid droplet-associated proteins FSP27/CIDEC and LSDP5, regulated directly by PPARγ and PPARα, are associated with hepatic steatosis and insulin sensitivity." (PMID 26770990, 2016). "In this study, we found that PPARγ is activated in alcohol-induced hepatic steatosis and associated with reducing SIRT1 activity upon ethanol metabolism." (PMID 27404390, 2016). "High PPARγ levels, in particular of PPARγ2, promotes de novo lipogenesis and liver steatosis and is associated with HFD feeding in mice." (PMID 28115925, 2016). "Further evidence for a coordinate responses in fatty liver disease was obtained by considering regulation of the ER lipid raft associated 2, PPARγ and insulin induced gene 1 by miR-192-5p." (PMID 27045805, 2016). "In support of the elevated TAG accumulation in Glmpgt/gt liver, the increased expression of PPARγ as seen in the Glmpgt/gt liver is a hallmark of hepatic steatosis, as it stimulates expression of lipogenic genes and the fatty acid transporter, CD36." (PMID 26047317, 2015). "On the other hand, the moderate reduction of PPARγ activity observed in heterozygous PPARγ-deficient mice and with the use of PPARγ antagonists has been reported to prevent fatty liver disease induced by HFD." (PMID 26317347, 2015). "SBS possesses a repressive property on hepatic steatosis, which is associated with inhibition of SREBP1c, PPARγ, ACC, DGAT2, and FAS, and induction of PPARα, suggesting a potential application of SBS in treatment of HFD-induced NAFLD." (PMID 24905748, 2014). "Mice fed a methionine-choline-deficient (MCD) diet developed severe hepatic steatosis, inflammation, and fibrosis with downregulation of Pparγ levels." (PMID 22966224, 2012). "In the leptin-deficient ob/ob mouse model of metabolic syndrome, PPARγ is critical for the development of hepatic steatosis, through modulation of its target protein fat-specific protein 27 (Fsp27)." (PMID 23028383, 2012). "Variants in the Pparγ gene found in human genotyping studies have been reported to affect hepatic steatosis." (PMID 22966224, 2012). "Med1 deficient livers fail to develop hepatic steatosis induced by glucorcorticoid receptor (GR) agonist and also fail to develop hepatic steatosis when induced by PPARγ overexpression (unpublished data)." (PMID 20814439, 2010). "It has been well established that in mouse models of steatosis,the development of fatty liver is associated with increasedhepatic expression of PPARγ." (PMID 17389767, 2007). "PAA was strongly associated with hepatic peroxisome proliferator-activated receptor gamma isoform 2 (Pparg2) activation in mice, which may represent the basis of the molecular mechanism underlying the association of gut bacteria and hepatic steatosis." (PMID 37922990, 2023). "Importantly, cyclin-D1-deficient mice develop hepatic steatosis, possibly because of overactivation of PPARγ." (PMID 36091143, 2022). "Hepatic PPARγ deficiency remarkably alleviates the fatty liver phenotype, clearly indicating that PPARγ is capable of activating the expression of genes involved in TG accumulation in hepatocytes and promoting the development of fatty liver." (PMID 35517790, 2022). "Overexpression of JMJD2B increased the expression of PPARγ and caused hepatic steatosis." (PMID 35412705, 2022). "Moreover, rosiglitazone, a PPARγ agonist, promoted mitochondrial dysfunction, oxidative stress, and liver steatosis in leptin-deficient mice." (PMID 33383845, 2020).
Hepatic steatosis (continued). "When PPARγ is overexpressed in the liver of mice, it causes hepatic steatosis." (PMID 31336903, 2019). "Upregulation of PPARγ has been reported to cause hepatic steatosis." (PMID 30405443, 2018). "Results in the present study showed that myricetin treatment could decrease hepatic PPARγ protein expression, as well as normalizing the relative expression of its target genes, which might be a cause for its role in regression of hepatic steatosis." (PMID 27973423, 2016). "Further study will be needed to determine whether this reduction of PPARγ is due to the loss of SRA itself or is a consequence of reduced hepatic steatosis via SRA deficiency." (PMID 27759039, 2016). "Pparγ, an upstream positive regulator of Cd36 expression, is also linked to hepatic steatosis." (PMID 26085100, 2015). "In animal models, TyG elevation promotes hepatic steatosis by activating PPARγ and Sterol Regulatory Element-Binding Protein 1c (SREBP-1c) pathways." (PMID 41056021, 2026). "This signaling pathway affects lipid metabolism in adipose tissue by influencing PPARγ expression and worsening hepatic steatosis." (PMID 40292292, 2025). "The involvement of PPARγ agonism in exacerbating hepatic steatosis and liver damage triggered by BBR in db/db mice was confirmed using a pharmacologically targeted strategy involving the administration of GW9662, a selective PPARγ antagonist." (PMID 39611414, 2025). "Previous literature reported that BMAL1 deletion inhibits the expression of CD36 and peroxisome proliferator-activated receptor γ (PPARγ) and attenuates hepatic steatosis." (PMID 40083324, 2025). "Thiazolidinediones (TZDs) are PPARγ agonists used in T2DM management, which have shown potential to reduce liver steatosis in MASLD and improve cardiovascular risk factors." (PMID 40869400, 2025). "Concurrently, THC intervention attenuated hepatic steatosis and fibrosis, mimicking the effects of the PPARG antagonist GW9662, which improves lipid metabolism in NASH mice." (PMID 40600138, 2025). "It is well known that the accumulation of PPARγ in the liver induces hepatic steatosis through the activation of lipogenic genes by increasing hepatic lipogenesis and triglyceride synthesis." (PMID 41462621, 2025). "In preclinical models, PPARγ overexpression exhibits protective effects by reducing hepatic steatosis, inflammatory infiltration, and fibrotic remodeling." (PMID 40564141, 2025). "Dysregulation of lipid-regulating factors were detected in hepatic tissue, with pharmacological inhibition of PPARγ ameliorating gestational BPA exposure-induced hepatic steatosis." (PMID 40475995, 2025). "To explore the possible mechanism by which calpain inhibition promotes hepatic steatosis, we evaluated the protein abundance of PPARγ, which is cleaved by CAPN1 in cell-free systems and promotes de novo lipogenesis in MASLD." (PMID 41468440, 2025). "Previous studies have demonstrated that hepatic IRF6, a transcription factor, serves as a critical factor in liver steatosis and exerts its role through negative regulation of PPARγ." (PMID 40235530, 2025). "Millet bran protein hydrolysate inhibits fatty acid uptake through PPARγ activation, alleviating hepatic steatosis and reducing lipid accumulation." (PMID 40507104, 2025). "BMAL1 ablation inhibits the expression of CD36 and PPARγ signaling and attenuates hepatic steatosis." (PMID 40083324, 2025). "This suggests that the prolonged accumulation of BBR and its metabolites due to impaired hepatic metabolism in hepatic steatosis results in sustained activation of PPARγ, thereby amplifying the PPARγ agonistic activity of administered BBR." (PMID 39611414, 2025). "Preclinical evidence shows that obese mice exhibit elevated PPARG expression, with PPARG agonists worsening hepatic steatosis; conversely, genetic deletion or downregulation of PPARG protects against steatosis." (PMID 40600138, 2025).
Hepatic steatosis (continued). "We showed that eight weeks of sucrose intake induces liver steatosis and fibrosis, which was associated with impaired CAPN1 activity and increases levels of PPARγ protein." (PMID 41468440, 2025). "In contrast, PPARγ and FAS are associated with the synthesis of fatty acids and contribute to the risk of fatty liver disease." (PMID 40730589, 2025). "PPARγ overexpression has been found to mitigate the effect on liver steatosis, a condition that can be alleviated by the administration of GW9662." (PMID 38276299, 2024). "atRA has also been reported to reduce hepatic lipid accumulation in liver steatosis model animals by repressing PPARγ and to induce lipolysis by a PPARβ/δ-mediated increase in the levels of HSL in adipocytes." (PMID 39032560, 2024). "PPARγ, known to promote hepatic lipid accumulation, plays a crucial role in hepatic steatosis by upregulating the expression of lipogenesis genes in diet-induced and genetically engineered obese mice." (PMID 38441531, 2024). "Our result indicated that SND1/H3K27me3/PPARγ is partially responsible for Sngh3-induced hepatic steatosis." (PMID 39436790, 2024). "To this end, we tested the effect of T0070907, a selective PPARγ antagonist, on Snhg3-induced hepatic steatosis in mice." (PMID 39436790, 2024). "Under normal conditions, PPARγ expression is very low in the liver and increased with the development of hepatic steatosis in rodents and humans." (PMID 38169398, 2024). "After OA-induced hepatic steatosis, we evaluated the expression of PPARγ and its downstream genes, including genes involved in lipid transport, synthesis, and β-oxidation, following treatment with celastrol, rosiglitazone, or GW9662." (PMID 38276299, 2024). "Overexpression of PPARγ can enhance hepatic steatosis but decrease steatosis conditions reported in the disruption of the PPARγ gene." (PMID 39759127, 2024). "According to our preliminary findings from in vitro celastrol signaling studies, PPARγ is likely to be the direct target of celastrol in regulating hepatic steatosis in HepG2 cells and adipocyte differentiation in 3T3-L1 cells." (PMID 38276299, 2024). "This study reveals a new signaling pathway, Snhg3/SND1/H3K27me3/PPARγ, responsible for hepatic steatosis and provides evidence of lncRNA-mediated epigenetics in the pathophysiology of MASLD." (PMID 39436790, 2024). "Take together, the findings of our research indicated that GW9662, a PPARγ inhibitor, and celastrol ameliorate OA-induced hepatic steatosis and that rosiglitazone exacerbates lipid accumulation." (PMID 38276299, 2024). "(G) Model of how Snhg3 and SND1 interacting and influencing chromatin remodeling via H3K27me3, and promoting PPARγ expression thereby resulting in hepatic steatosis." (PMID 39436790, 2024). "Consistently, the knockout of PPARγ in db/db mice noticeably mitigated hepatic steatosis by downregulating the expression of genes such as FAS, SCD1, and ACC." (PMID 38441531, 2024). "The PPARγ signaling pathway was reduced in Hilnc knockout mice, which made them resistant to diet-induced obesity and hepatic steatosis." (PMID 37190114, 2023). "Polyphenols present in PE-TFG extract improve the expression of adiponectin; thereby, PPARγ helps in the prevention of hepatic steatosis." (PMID 37520342, 2023). "The role of PPARγ signaling in the liver is not yet fully understood, since both, the promotion and the prevention of hepatic steatosis have been observed for PPARγ agonists." (PMID 36769005, 2023). "PPARγ is an additional reinforcing lipogenic signal that assists sterol regulatory element-binding protein-1c in triggering hepatic steatosis development." (PMID 36670177, 2023). "Among the various PPAR subtypes, PPARγ plays a pivotal role in promoting hepatic steatosis by increasing the expression of SREBP-1c." (PMID 38136160, 2023). "PPARγ mainly promotes lipogenesis and preadipocyte differentiation and its upregulation contributes to hepatic steatosis." (PMID 37533076, 2023).